HLA-C (major histocompatibility complex, class I, C)
Diseases named in the same sentence as HLA-C in open-access papers (continued):
Sharing a sentence is not in itself a finding about the gene and the disease.
psoriasis (continued). "Within the MHC, HLA-C*06 is the allele that shows the strongest association with psoriasis." (PMID 24600518, 2014). "However, the patients with allele 384 of the C1_4_4 microsatellite, telomeric to HLA-C, were significantly older at the onset of psoriasis (35.3 ± 12.6 versus 25.1 ± 13.7 years, P = 0.01) and of arthritis (42 ± 11.5 versus 33 ± 11.7 years, P = 0.01)." (PMID 23690822, 2013). "The HLA-C region has been associated particularly with Behçet disease, psoriasis, and sarcoidosis." (PMID 24324648, 2013). "We note, however, that among all HLA-C allotypes, HLA-C*06:02 shows the highest level of cell surface expression, which could explain, to some extent, its strong association with psoriasis." (PMID 22577363, 2012). "Psoriasis patients are more likely to harbor alleles such as HLA-B*57, HLA-B*27, HLA-C*06 (in high LD with the HLA-C 3′UTR deletion polymorphism), and KIR3DS1+Bw4-80I, theoretically resulting in vigorous cytotoxic T cell and NK cell responses upon infection with HIV-1 virus." (PMID 22577363, 2012). "We additionally performed stepwise regression to identify amino acid residues that were independently associated with psoriasis and found Trp156 and Ala24 in HLA-C; Val97, Leu145, Cys67, and Tyr99 in HLA-B; and Gly107 in HLA-A to be markers independently associated with psoriasis." (PMID 22577363, 2012). "PSORS1C3 is located in the major histocompatability (MHC) region, and subsequent papers have found that the associations with psoriasis may be due to variants in HLA-C (MIM 142840)." (PMID 21949713, 2011). "More importantly we find that rs9468925 in HLA-C/HLA-B is associated with both psoriasis and vitiligo, providing first important evidence that two major skin diseases share a common genetic locus in the MHC, and a basis for elucidating the molecular mechanism of skin disorders." (PMID 22125590, 2011). "The association of HLA-C with psoriasis was first proposed as early as 30 years ago." (PMID 19680446, 2009). "Located 85 kb centromeric to HLA-C, HLA-B has also repeatedly exhibited association with psoriasis." (PMID 19680446, 2009). "Moreover, the results of HLA-C tagging SNPs, known to be strongly associated with psoriasis, illustrated the weak power of Set II for performing family-based association tests." (PMID 17878941, 2007). "Strong association of HLA-C with psoriasis was detected and presumed to be the etiological variant, until further studies suggested that the true etiological variant actually lies 60kb outside of the HLA-C molecule." (PMID 19412418, 2007). "HLA-Cw*0602 seems to confer a general risk for psoriasis, but the presence of other HLA-C locus alleles may explain an additional arthritogenic risk." (PMID 17166285, 2006). "In addition, cytotoxic CD8+ T (Tc) cells can also express IL-17A (Tc17) upon recognition of the self-antigen ADAMTSL5 via HLA-C*06:02 which is the strongest psoriasis susceptibility allele in psoriasis patients revealing their pivotal pathogenic role in psoriasis." (PMID 37594540, 2023). "Notably, an ERAP1 risk haplotype for psoriasis, including the same variants analysed in this study, has been proven to efficiently generate a melanocyte-derived autoantigen with a parallel increase of the predisposing HLA-C*06:02 molecules." (PMID 37686141, 2023). "Interestingly, streptococcal infections are more common in those with the psoriasis susceptibility HLA-C*06:02 allele, which may explain why psoriasis patients have an increased burden of streptococcal infections than healthy controls." (PMID 34639182, 2021). "Likewise, rs12191877 in HLA-C has been associated with increased risk of psoriasis." (PMID 26613086, 2015). "Interestingly, the HLA-C locus has been reported as a major determinant of susceptibility to psoriasis, an inflammatory skin disorder with a strong genetic component, and the low expressing T allele of the −35 kb SNP is associated with an increased risk of the disease." (PMID 25083782, 2014).
psoriasis (continued). "Additionally, other MHC genes have also been associated with psoriasis independently of HLA-C*06." (PMID 23690822, 2013). "In order to determine whether HLA-C*06 and, respectively, other alleles are associated with PsA itself or primarily with psoriasis, we have compared the allele frequencies obtained in psoriatic patients with PsA with frequencies in patients having psoriasis alone." (PMID 23184486, 2013). "Second, vitiligo and psoriasis share some common susceptibility genes (e.g., IFIH1, BTNL2) and genetic loci (e.g., HLA-C/HLA-B rs9468925)." (PMID 40156617, 2025). "The immunogenicity of melanocytes depends on IFN-γ, which is abundantly expressed in psoriasis lesions and upregulates HLA-C and ERAP1 that are both highly expressed by melanocytes in the basal epidermal layers of psoriasis lesions." (PMID 40243413, 2025). "Our findings further suggest targeting the expression of HLA-C*06:02 as a strategy for the development of new therapeutic concepts for psoriasis." (PMID 40243413, 2025). "In psoriasis, HLA-C is highly expressed on melanocytes in the basal epidermal layers of psoriatic plaques." (PMID 40243413, 2025). "We observed that PBMCs from HLA-C*06:02+ psoriasis patients exhibited significantly higher autoproliferation (AP) compared to healthy individuals (each n = 7)." (PMID 41440022, 2025). "Further, the Vα3S1/Vβ13S1 TCR was stimulated by HLA-C*06:02+ B cells of various origins, and blood-derived B cells from psoriasis patients induced autoproliferation of CD8+ T cells in the autologous mixed lymphocyte reaction." (PMID 41440022, 2025). "The risk of psoriasis is increased by epistasis between HLA-C*06:02 and the enzymatically highly active ERAP1 haplotype Hap2, while the low-activity haplotype Hap10 protects against psoriasis." (PMID 41440022, 2025). "Using an experimental model that reproduces the HLA-C*06:02-restricted autoimmune response of CD8+ T-cells against melanocytes in psoriasis, we identified a potential mechanism of action of UVB phototherapy." (PMID 40243413, 2025). "For example, specific HLA-C alleles have been shown to be associated with viral infections (e.g., HIV), autoimmune diseases (e.g., psoriasis), and transplant rejection." (PMID 40692979, 2025). "HLA-B*27+ patients not responding to UVB phototherapy would be consistent with the observation that it is the HLA-C-restricted autoimmune response in psoriasis that responds so well to treatment with UVB irradiation." (PMID 40243413, 2025). "Screening tonsillar cells from HLA-C*06:02+ patients tonsillectomized due to streptococcal-induced psoriasis, we unexpectedly discovered that B cells stimulate the melanocyte-reactive Vα3S1/Vβ13S1 TCR." (PMID 41440022, 2025). "We now find that this TCR is also stimulated by HLA-C*06:02+ B cells originating from both tonsils and peripheral blood of psoriasis patients." (PMID 41440022, 2025). "To identify potential triggers of the lesional psoriatic autoimmune response, we prepared single-cell suspensions from tonsils of three HLA-C*06:02+ psoriasis patients who had undergone tonsillectomy due to recurrent streptococci-driven psoriasis." (PMID 41440022, 2025). "When PBMC were examined, the ADAMTSL5- and wheat-peptide loaded HLA-C*06:02 tetramers stained significantly more CD8+ T cells of HLA-C*06:02+ psoriasis patients than of HLA-C*06:02+ healthy subjects." (PMID 38524140, 2024). "A study showed that there is an interaction effect between HLA-C and ERAP1 in psoriasis, and ERAP1 variants influence psoriasis susceptibility only in individuals carrying the HLA-C risk allele." (PMID 39156563, 2024). "In this study we evaluated PRS-ALL, PRS-noHLA, PRS-HLA, and HLA-C*06:02 on age of onset, psoriatic arthritis, psoriasis body location, psoriasis subtype, psoriasis environmental triggers, co-morbidities, and treatment response in different racial groups." (PMID 39261909, 2024).
psoriasis (continued). "We investigated the immunogenicity of these peptides for psoriasis patients and healthy controls by lymphocyte stimulation experiments and peptide-loaded HLA-C*06:02 tetramers." (PMID 38524140, 2024). "Our psoriasis subtype results showed that HLA-C*06:02 was driving guttate psoriasis in the combined cohort." (PMID 39261909, 2024). "The *01:03 allele alters the presentation of the psoriasis-inducing self-determinant by HLA-C, which provides the protection against psoriasis." (PMID 36899273, 2023). "Whereas the correlation of HLA-C*06:02 with psoriasis is more pronounced than with psoriatic arthritis, other HLA variants such as HLA-B*27, HLA-B*39, HLA-B*38, and HLA-B*08 have been related with the development of psoriatic arthritis." (PMID 37628670, 2023). "Increased p16 and HLA-C promoter methylation, and decreased HLA-DRB1 promoter methylation were significantly associated with the Psoriasis Area Severity Index (PASI score)." (PMID 36319514, 2023). "The type I human leukocyte antigens (HLA) gene HLA-C exhibits a consequential reliance of vulnerability to psoriasis throughout the major histocompatibility complex (MHC)." (PMID 37965393, 2023). "Hypermethylated promoters in p15, p16, p21, ID4, IFNG, and HLA-C genes affect their expression in psoriasis." (PMID 36319514, 2023). "Thus, it may cause psoriasis lesions by interacting with HLA-C." (PMID 36425068, 2022). "The PSORS1C1 gene, located 127 kb telomeric to the HLA-C locus, is considered to be one of the potential candidate genes for psoriasis." (PMID 36078103, 2022). "It is an interesting finding since CD8+ T cell autoreactivity against a melanocyte antigen presented on HLA-C*06:02 was demonstrated in psoriasis and peptide-binding properties of HLA-C*06:02 and -B*27 overlap." (PMID 33581710, 2021). "A fascinating case study with a unique methodology identified ADAMTS-like 5 (ADAMTSL5) as an HLA-C*06:02-presented melanocytic autoantigen to the lesion-infiltrating autoreactive CD8+ T cells in psoriasis." (PMID 33581710, 2021). "HLA-C*06:02, which also interacts strongly with KIR, is strongly associated with psoriasis, an immune-mediated disease." (PMID 34002224, 2021). "They demonstrated that HLA-C*06:02-negative patients with psoriasis are significantly more likely to respond to adalimumab than to ustekinumab but that there is no significant benefit to adalimumab over ustekinumab in HLA-C*06:02-positive patients." (PMID 32998429, 2020). "The functional role of HLA-C in the pathogenesis of psoriasis is unclear; the major role of HLA-C has been assumed to be related to antigen presentation to CD8+ T-cells." (PMID 33419370, 2020). "Other risk factors in Psoriasis are allelic variants of ERAP1, such as rs27524 (noncoding) and rs30187 (K528) (in epistasis with HLA-C*06:02), included in the Hap2 risk haplotype." (PMID 33348540, 2020). "Variation in the HLA-C gene contributes to psoriatic heredity, by which HLA-C*06 is related to psoriasis patients in White and Chinese populations." (PMID 31736959, 2019). "Of note, both antigens are recognized by T cells when being presented by HLA-C*06:02, i.e., the most prominent psoriasis risk gene in the genome [located on PSORS1 (psoriasis susceptibility locus 1) on chromosome 6p21.3]." (PMID 31402919, 2019). "A more recent strategy to identify potential targets of pathogenic T-cells in psoriasis was based on the generation of T-cell hybridomas expressing the paired Vα3S1/Vβ13S1 TCR of clonal CD8+ psoriatic T cells of an HLA-C*06:02-expressing psoriasis patient." (PMID 31402919, 2019). "HLA-C*06:02, and other psoriasis-related HLA types such as HLA-C*07:01, HLA-C*07:02, and HLA-B*27 utilize identical anchor residues and present partially overlapping peptide residues." (PMID 31402919, 2019). "Still, a Japanese-specific reference panel showed increased odds ratios for HLA-C*06:02, HLA-C*12:02, and HLA-C*07:04 in the Japanese psoriasis population." (PMID 29760713, 2018).
psoriasis (continued). "More recent investigation into the classification of early onset psoriasis has confirmed the association of ERAP1 rs30187 and rs27044 (K528R and Q730E) only in HLA-C*06 positive individuals." (PMID 30054427, 2018). "Of these, three (HLA-C, CCHCR1 and CDSN) were highly polymorphic and harbored coding variants that were significantly associated with psoriasis." (PMID 29186830, 2017). "Similar epistatic effects were also observed for psoriasis, such that individuals who carry variants in ERAP1 showed an increased risk only when they also carried an HLA-C risk allele." (PMID 28449694, 2017). "Compared to HLA-C*06 alone, this effect provides only scant explanation of complexity in genetics of psoriasis." (PMID 27658291, 2016). "The recognition of this protein is restricted to epidermal CD8+ T cells of patients with psoriasis and a HLA-C*06:02 genotype." (PMID 27158469, 2016). "Comparison between patients with type I psoriasis and patients with type II psoriasis revealed significant associations for the following genes: FCGR2A, TNFR1, CD226, PSORS6, TNFAIP3, HLA-C, TNF-α, and CCHCR1." (PMID 26613086, 2015). "Patients suffering psoriasis alone showed a higher frequency of HLA-C*06, C1_4_4 microsatellite, OTFHind3 gen, and HCR gen." (PMID 24600518, 2014). "As a whole, our results point to the region telomeric to HLA-C as being important for psoriasis development, whereas the centromeric region seems to play a key role in susceptibility and disease expression in PsA." (PMID 24600518, 2014). "We found that rs10484554 and rs12191877 near HLA-C and rs17716942 near IFIH1 were associated with age onset of psoriasis with FDR_q value < 0.05." (PMID 24175098, 2013). "On the other hand, the developmental context for each psoriasis lesion is patient-specific and likely shaped by an integration of genetic (e.g., HLA-C genotype, etc.)and environmental signals (e.g., diet, smoking status, sun exposure)." (PMID 23915137, 2013). "The men developing psoriasis before 40 years of age (n = 45) showed over-expression of the following markers: HLA-C*06 (58% versus 18.2%." (PMID 23690822, 2013). "We found that rs10484554 and rs12191877 near HLA-C and rs17716942 near IFIH1 were associated with age of psoriasis onset with false discovery rate < 0.05." (PMID 24175098, 2013). "The women developing psoriasis before 40 years of age (n = 40) showed significant elevation of the following markers versus the female control population: HLA-C*06 (65% versus 16.4%." (PMID 23690822, 2013). "In this study we found that among the many psoriasis loci discovered by GWAS, only the HLA-C locus showed robust evidence of playing a role in earlier psoriasis onset." (PMID 24175098, 2013). "Hereby, we provide the first report on the association of HLA-C, DRB1 and DQB1 alleles with psoriasis in the Slovak population." (PMID 23184486, 2013). "Though HLA-C*06 is undoubtedly associated with PV, limited data exist to explain the functional role of HLA-C in the pathogenesis of psoriasis." (PMID 23184486, 2013). "In the German, Italian and Thai population, the extended haplotype (EH) HLA-C*06-B57-DRB1*0701-DQA1*0201-DQB1*0303, named according to the B allele EH-57.1, was reported to be highly overrepresented in patients with psoriasis." (PMID 23184486, 2013). "The men developing psoriasis after 40 years of age (n = 10) in turn showed a significant increase in the following markers: HLA-C*06 (50% versus 18.2%." (PMID 23690822, 2013). "The two most significant SNPs identified in multiple psoriasis GWAS are rs10484554 and rs12191877 near HLA-C (r2 = 1 with each other in Europeans)." (PMID 22577363, 2012). "With four regression models obtained, two SNPs rs9468925 in HLA-C/HLA-B and rs2858881 in HLA-DQA2 were repeatedly selected in all models, suggesting that multiple loci outside PSOR1 locus were associated with psoriasis." (PMID 22125590, 2011).
psoriasis (continued). "There was a statistically significant difference between PsA and psoriasis alone at three loci (HLA-C, IL-12B and IL-23R)." (PMID 20606885, 2010). "The second locus we observed after adjustment for HLA-C and C6orf10 is between HLA-B and MICA, located 117 kb centromeric to HLA-C, suggesting the potential association of HLA-B or MICA with psoriasis risk." (PMID 19680446, 2009). "To investigate the mechanisms underlying the efficacy of phototherapy in psoriasis, we have now examined the impact of UVB irradiation on the ability of melanocytes to stimulate the HLA-C*06:02-restricted Vα3S1/Vβ13S1 TCR in an in vitro assay that models the autoimmune response in psoriasis." (PMID 40243413, 2025). "Melanocytes have also been recently proposed as target cells of the HLA-C*06:02-restricted autoimmune response in psoriasis via the melanocyte autoantigen ADAMTSL5, which could provide a skin-specific target for autoimmune attack." (PMID 40021644, 2025). "Key genetic loci such as HLA-C, TNIP1, IL12B, and IL23R are linked to psoriasis." (PMID 40557155, 2025). "Here we find that B cells isolated from streptococci-infected tonsils or peripheral blood of HLA-C*06:02+ psoriasis patients stimulate an HLA-C*06:02-restricted melanocyte-reactive Vα3S1/Vβ13S1 T-cell receptor (TCR) from a lesional psoriatic CD8+ T cell clone in an IFN-γ-enhanced manner." (PMID 41440022, 2025). "In addition, the HLA-C phenotype found in the AGS patient showed C*02 and C*12 alleles, suggesting susceptibility to severe psoriasis." (PMID 39859393, 2025). "Likewise, in psoriasis, ERAP1 variants rs30187 (K528R) and rs2287987 (M349V) contribute to inappropriate inflammatory responses through altered interactions with the HLA-C*06:02 molecule, a known psoriasis risk allele." (PMID 40226591, 2025). "SFRP2+ fibroblasts were reported to overexpress ERAP2 and HLA-C in psoriasis." (PMID 40574847, 2025). "Hence, the generation of the psoriatic autoantigen by ERAP1 and its presentation by HLA-C*06:02 on melanocytes are essential events in the induction of the autoimmune response by CD8+ T-cells in psoriasis." (PMID 40243413, 2025). "There exists more clear evidence regarding the risk conferred by HLA-ABC alleles to other autoimmune diseases, with associations reported for HLA-B*27 and ankylosing spondylitis, HLA-C*06:02 and psoriasis, HLA-B*51 and Behçet’s disease, and HLA-A*29 with birdshot chorioretinopathy." (PMID 41444678, 2025). "This indicates that HLA-C*06:02 may be protective for PsA amongst a cohort of individuals with psoriasis." (PMID 39261909, 2024). "Finally, NGS analysis revealed that all patients carried several allelic variants in psoriasis susceptibility genes, such as HLA-C, ERAP1 and other genes of the major psoriasis susceptibility PSORS1 locus." (PMID 38495872, 2024). "Certain genes, like HLA-C, IL23R, IL12B, and LCE3B/3C, increase susceptibility to psoriasis." (PMID 38022642, 2023). "Although the exact role of HLA-C in psoriasis development remains unclear, there seems to be an interplay/relation between HLA-Cw6 status and immune dysregulation in psoriasis patients." (PMID 37405259, 2023). "We also found multiple associations in rare alleles (MAF < 1%), including the novel HLA-B*57:31:02 in psoriasis (OR = 4.61, 95% CI: 3.22–6.59, p = 7.1 × 10−17, EAF = 0.06%) and HLA-C*02:178 in ankylosing spondylitis (OR = 5.33, 95% CI: 3.37–8.41, p = 7.75 × 10−13, EAF = 0.2%)." (PMID 37923823, 2023). "Only a few studies reported the correlation between HLA-C*07 and psoriasis." (PMID 36826011, 2023). "Psoriasis, a relatively common skin disease, is associated with HLA-C*06:02, although some 30% of patients do not possess this allele." (PMID 35769458, 2022). "Additionally, the methylation level of HLA-C promoter region in psoriasis patients was significantly higher than that in healthy controls." (PMID 36193416, 2022). "The HLA-C haplotype has been extensively studied in psoriasis." (PMID 33921427, 2021).